NOS2 (nitric oxide synthase 2)
Diseases named in the same sentence as NOS2 in open-access papers (continued):
Sharing a sentence is not in itself a finding about the gene and the disease.
Giardia infection (2 papers, 2013 to 2019). "We have previously reported an accumulation of ARG1- and NOS2-expressing macrophages in the small intestine during Giardia infection, and this expression was confirmed in the macrophages described in this study." (PMID 31455692, 2019). "We show that a population of F4/80+, CD11b+, CD11cint, CX3CR1+, MHCII+, Ly6C−, ARG1+, and NOS2+ macrophages accumulate in the mouse small intestine during Giardia infection." (PMID 31455692, 2019). "The profile of nos2 induction in low-arginine medium was similar to the profile induced by Giardia infection with a peak of expression after 6 h." (PMID 24228819, 2013). "We have previously demonstrated that Giardia infection leads to the accumulation of a population of CD11b+, F4/80+, ARG1+, and NOS2+ macrophages in the small intestinal lamina propria." (PMID 31455692, 2019).
Headache (2 papers, 2021 to 2023). Cephalgia, or pain sensed in various parts of the head, not confined to the area of distribution of any nerve. "Over the past 15 years, works aimed at finding associations of NOS1, NOS2, and NOS3 genes with the development and course of headaches (H) have been carried out using the example of patients with M." (PMID 34200123, 2021). "Then, we compared the allele frequencies of the SNP rs2779249 of the NOS2 gene between hypertensive patients with TTH and without headache (OS and AH groups)." (PMID 36833440, 2023). "In addition, we compared allele frequencies of the SNP rs2297518 of the NOS2 gene between hypertensive patients with TTH and without headache (OS and AH groups)." (PMID 36833440, 2023).
Hepatitis (2 papers, 2014 to 2022). Inflammation of the liver. "Basic pharmacological studies also showed that GL could prevent hepatitis induced by concanavalin A (Con A) through inhibiting liver iNOS (nitric oxide synthase 2, inducible) induction and hepatocyte degeneration." (PMID 36313350, 2022).
hydatid disease (2 papers, 2009 to 2024). "Previous studies have suggested that as hydatid disease progresses, there appears to be a tendency to induce a low NOS2-expressing phenotype in host immune cells like macrophages, T cells, and B cells." (PMID 38655088, 2024). "Furthermore, Human inducible NO synthase (NOS2) expression during hydatidosis has been detected in liver biopsies from patients by immunochemical method." (PMID 20798753, 2009).
hyperhomocysteinemia (2 papers, 2010 to 2023). A serious metabolic condition caused by mutations in the MTHFR gene, medications, or nutritional deficiency. "Thus, low folic acid intake and resulting hyperhomocysteinemia may interact with NOS2 polymorphisms to influence the risk of CTD." (PMID 36672920, 2023).
hypothyroidism (2 papers, 2022 to 2025). Abnormally low levels of thyroid hormone. "The reduced expression of IL-10, NOS2 and IFN-γ in the placenta of rats with hypothyroidism has supported this." (PMID 41282300, 2025).
infertile (2 papers, 2009 to 2024). "Between Period 1 and 2, there was a decrease in the level of expression of IL6 (P < 0.05) and NOS2 (P < 0.05) in infertile animals and NOS2 (P < 0.05) for fertile animals." (PMID 19476661, 2009). "The levels of IFN-a, TNF and NOS2 were similar for fertile and infertile animals during Period 1, although IL6 tended to be higher in infertile animals (P = 0.06)." (PMID 19476661, 2009).
invasive breast carcinoma (2 papers, 2015 to 2017). A carcinoma that infiltrates the breast parenchyma. "In invasive breast carcinoma (n = 53) NOS2 expression was significantly increased (p = 7.19E-9) compared to normal stromal breast tissue (n = 6)." (PMID 28340615, 2017). "We report that NOS2 is commonly increased in invasive TNBC and is associated with poor survival of patients with invasive breast carcinoma." (PMID 25849745, 2015).
keratoconus (2 papers, 2021 to 2023). A degenerative, structural disorder of the eye, characterized by a cone-shaped protrusion of the cornea. "We overlaid these 4 modules with FRGs and found that 8 FRGs (LCE2C, NOS2, AKR1C3, CAV1, MMD, LINC00618, SNCA, SLC7A11) were closely related to the disease state of keratoconus." (PMID 37626095, 2023).
kidney (2 papers, 2015 to 2025). "Several SNPs in NOS2 have been associated with gastric, esophageal, skin and urogenital cancers." (PMID 26301412, 2015).
kidney damage (2 papers, 2017 to 2021). "PFD treatment significantly inhibited the expression of TNF-α, IL-6, and nitric oxide synthase-2 by M1 macrophages, suggesting its efficacy in the early and late periods of kidney damage." (PMID 33520317, 2021).
Listeria infection (2 papers, 2019 to 2021). "Interestingly, the IRF9, STAT1, STA3, and NF-κB can bind to promoter region of Nos2 gene and induce its transcription during Listeria monocytogenes infection, suggesting both direct and indirect routes for miR-302d regulation of Nos2 expression." (PMID 30949455, 2019).
liver disease (2 papers, 2014 to 2026). "Finally, studies with HBV, a hepadnavirus associated with acute and chronic hepatitis, demonstrated that HBV replicated to higher levels in the livers of HBV-transgenic Nos2−/− mice than control transgenic mice, and transgenic Nos2−/− mice had increased liver disease." (PMID 25250029, 2014).
Marfan syndrome (2 papers, 2024 to 2025). A disorder of the connective tissue. "A recent study demonstrated that VCAN contributes to aortic disease in Marfan syndrome (MFS) by triggering Nos2 through Akt activation in vivo." (PMID 40227858, 2025).
meningitis (2 papers, 2013 to 2014). A disorder characterized by acute inflammation of the meninges of the brain and/or spinal cord. "Notably, in experimental meningitis, PARP1-deficient mice and mice treated with the PARP inhibitor, 3 aminobenzamide (3-AB), display reduced leukocyte infiltration and meningeal inflammation, and this is correlated with impaired expression of Il1β, Il6 and Nos2." (PMID 25161822, 2014).
metastatic colorectal cancer (2 papers, 2018 to 2025). "In this context, we investigated the prognostic and predictive significance of the NOS2/ARG1 axis and immune cell ratios in chemotherapy combined with cetuximab in wt-KRAS metastatic colorectal cancer." (PMID 41573553, 2025).
neuropathy (2 papers, 2017). A disorder affecting the nervous system that manifests with pain, tingling, numbness, and/or muscle weakness. "We have shown that the inhibition of NF-κB with a potent inhibitor, parthenolide, not only diminished the symptoms of neuropathy but also potentiated morphine analgesia and reduced the levels of pro-inflammatory factors produced by microglia (IL-1β, IL-18, NOS2)." (PMID 28491822, 2017).
ocular hypertension (2 papers, 2007 to 2013). Abnormally high intraocular pressure. "No significant increase in NOS2 expression (at the protein or message level) was found in optic nerve head cells due to ocular hypertension." (PMID 18093296, 2007).
pulmonary arterial hypertension (2 papers, 2006 to 2024). Pulmonary arterial hypertension (PAH) is a group of diseases characterized by mean pulmonary artery pressure >20 mmHg and elevated pulmonary arterial resistance leading to right heart failure. "iNOS, also known as NOS2, catalyzes the production of NO, and a decrease in iNOS results in a reduction in NO content, which in turn leads to pulmonary hypertension and increased pulmonary vascular permeability, exceeding the compensatory capacity of the body, which ultimately leads to HAPE." (PMID 37165489, 2024).
rectal cancer (2 papers, 2014 to 2024). A primary or metastatic malignant neoplasm that affects the rectum. "The minor allele A of the NOS2 genotype was observed more frequently in right-sided cancers than in left-sided cancers (44.9% vs. 23.1%, p = 0.0137) and more frequently in rectal cancers than in left-sided cancers (40.0% vs. 23.1%, p = 0.0285)." (PMID 38398251, 2024). "The presence of allele A in the NOS2 genotype increases the chances of rectal cancer by over two times compared to left-sided cancers [OR = 2.22, 95%CI: 1.08–4.55, p = 0.0302]." (PMID 38398251, 2024).
retinal disease (2 papers, 2009 to 2021). "NOS2 is involved in the pathogenesis of various retinopathies including retinal disease caused by I-R." (PMID 19626134, 2009).
schistosomiasis (2 papers, 2009 to 2016). An infectious disease caused by parasitic trematodes of the genus Schistosoma that colonize human blood vessels and release eggs that can cause granulomatous reactions leading to acute (swimmer's itch or acute schistosomiasis syndrome) or chronic disease. "It had been confirmed that Th1 immunity, CAMs, and expression of NOS-2 correlate with acute mortality in schistosomiasis, while Th2 cytokine, AAMs activation, and Arg-1 expression correspond to fibrogenesis." (PMID 27875565, 2016). "Strikingly, in contrast to the findings with Il4ra−/flox;LysMcre mice, our data suggest that Arg1-expressing AAMs are not required to suppress acute Th1/NOS2/LPS-mediated morbidity and mortality in schistosomiasis." (PMID 19360123, 2009).
scleroderma (2 papers, 2019 to 2021). Scleroderma is a rare autoimmune connective tissue disorder characterized by abnormal hardening of the skin and, sometimes, other organs. "The number of M1 macrophages, which include CD68+TLR2+ and CD68+NOS2+ cells, were increased in BLM-treated scleroderma skin, and EchA co-treatment reduced the number of M1 macrophages." (PMID 33922418, 2021). "Therefore, we quantified the numbers of M2 macrophages, which include CD68+CD163+ or CD68+Arginase-I+ populations, and M1 macrophages including CD68+NOS2+ and CD68+TLR2+ populations in scleroderma skin." (PMID 31552041, 2019). "Moreover, the numbers of M1 macrophages including CD68+NOS2+ and CD68+TLR2+ populations increased in BLM-induced scleroderma skin; however, the BLM-induced increase of M1 macrophage (CD68+NOS2+ and CD68+TLR2+) populations was not significantly affected by WKYMVm treatment." (PMID 31552041, 2019).
Senile plaques (2 papers, 2015 to 2016). Senile plaques are extracellular deposits of amyloid in the gray matter of the brain. "Likewise, inflammation-driven induction of NOS2 which goes along with massive production of nitric oxide induces the nitration-induced aggregation of Aβ in senile plaques." (PMID 24838579, 2015).
small cell lung carcinoma (2 papers, 2023). Small cell lung cancer (SCLC) is a highly aggressive malignant neoplasm, accounting for 10-15% of lung cancer cases, characterized byrapid growth, and early metastasis. "BIRC3 and NOS2 were closely associated with small-cell lung cancer pathways." (PMID 37842046, 2023).
sporotrichosis (2 papers, 2018). The commonest and least serious of the deep mycoses, characterized by nodular lesions of the cutaneous and subcutaneous tissues. "In fact, in skin lesions from sporotrichosis patients (humans), NOS2 expression was associated with more extended and severe lesions such as the lymphocutaneous form as well as to higher fungal load, suggesting that NO may induce tissue damage favoring fungal spread." (PMID 30065160, 2018). "LCL-ATL and SCL-ATL had a significantly higher percentage of CD8, FasL and NOS2 than sporotrichosis." (PMID 29440688, 2018). "For example, in a comparative study on the immunopathology of tegumentary leishmaniasis and sporotrichosis, the lesions were macroscopically very similar, however microscopically, they differed in quantities of neutrophils, macrophages, CD8 T cells, CD4 T cells, NOS2, B cells, and FasL+ cells." (PMID 30065160, 2018).
ulcer (2 papers, 2020 to 2022). "The production of NOS2/NO contributes to chronic inflammation of ulcers through stimulating the synthesis of prostaglandin E2 and cyclooxygenase-2." (PMID 32276345, 2020). "It has also been reported that NOS2 expression is increased in experimental small intestinal ulcers and that the degree of expression correlates with inflammation, and NOS enzyme inhibitors can promote ulcer healing and alleviate inflammation." (PMID 36714107, 2022).
Abdominal obesity (1 paper, 2020). Excessive fat around the stomach and abdomen. "Abdominal obesity increases free fatty acids in the liver, which induces superoxide anion formation and up-regulates Nos2 gene expression to result in peroxynitrite synthesis and to lead to both mitochondrial dysfunction and liver injury." (PMID 32961723, 2020).
Achalasia (1 paper, 2024). A disorder of esophageal motility characterized by the inability of the lower esophageal sphincter to relax during swallowing and by inadequate or lacking peristalsis in the lower half of the body of the esophagus. "Next, the correlation between the polymorphic pentanucleotide (CCTTT)n in the promoter of the NOS2 gene and achalasia was evaluated in another study, obtaining an association with the disease likely through an allele-specific modulation of NO synthesis." (PMID 39337632, 2024).
Acidosis (1 paper, 2020). Abnormal acid accumulation or depletion of base. "Acidosis decreased the gene expression of the pro-inflammatory markers Nos2, Ccl2, and IL-6 in IFN-γ/lipopolysaccharide-polarized macrophages, and it increased the expression of anti-inflammatory markers CD206 and Arg1 in IL-4-polarized macrophages." (PMID 32823915, 2020).
acute liver failure (1 paper, 2024). Rapid deterioration of liver function causing encephalopathy and coagulopathy. "The PPARδ agonist GW501516 improves survival in a mouse model of acute liver failure induced by LPS/D-GalN, primarily by suppressing the expression of pro-inflammatory cytokines such as TNF-α, IL-6, and NOS2 in vivo." (PMID 39519830, 2024).
alcoholic liver diseases (1 paper, 2019). A disorder caused by damage to the liver parenchyma due to alcohol consumption. "As discussed in Section 3.2, “Target prediction of TCM,” ZZDHT decoction has been applied to treat alcoholic liver disease by targeting CYP2E1, XDH, NOS2, and PTGS2." (PMID 30846939, 2019). "The authors found that ZZDHT may exert antioxidant effects to regulate reactive oxygen species, thereby treating alcoholic liver disease by targeting cytochrome P450 2E1 (CYP2E1), xanthine dehydrogenase (XDH), nitric oxide synthase 2 (NOS2), and prostaglandin-endoperoxide synthase 2 (PTGS2)." (PMID 30846939, 2019).
aplastic anemia (1 paper, 2018). Anemia resulting from bone marrow failure (aplastic or hypoplastic bone marrow). "High expression IFN-γ of TNF-β in the bone marrow cells of aplastic anemia patients can accelerate NOS2 expression of CD34+ cells and result in the apparent increase in CD34+ cell apoptosis rate." (PMID 29736233, 2018). "High expression of interferon-γ (IFN-γ) or tumor necrosis factor-β (TNF-β) in patients with aplastic anemia can accelerate NOS2 expression in CD34+ cells and may increase the apoptosis rate of CD34+ cells." (PMID 29736233, 2018).
astrocytoma (1 paper, 2017). "This is emphasized by the negative prognostic effect of VAV3 and NOS2 expression in grade IV astrocytoma and for SPC24 in liver tumours." (PMID 29152145, 2017).
autism spectrum disorder (1 paper, 2020). A spectrum of developmental disorders that includes autism, and Asperger syndrome. "Unlike NOS2, the association study of NOS1 and NOS2 genes (see Section 2.3.2 “Autism Spectrum Disorders” regarding NOS2) with autism spectrum disorders (ASD) in an Asian population demonstrated no statistically significant results with respect toNOS1." (PMID 32111088, 2020).
autoimmune myocarditis (1 paper, 2012). Autoimmune myocarditis is an autoimmune disease that affects the heart. "Interestingly, iNOS/NOS2 upregulation in an inflammatory milieu results in increased NO levels in the cardiac tissue in autoimmune myocarditis." (PMID 22590660, 2012).
basophilic leukemia (1 paper, 2016). "NOS1, inducible NOS (NOS2) and NOS3 have been found in human mast cell (HMC)-1 cell line, NOS3 has been found in rat basophilic leukemia RBL-2H3 cell line and NOS2 is expressed in P815 mouse mastocytoma cell line." (PMID 27538454, 2016).
biliary tract cancer (1 paper, 2012). "Data from our population-based study of biliary tract cancers in Shanghai suggested that variants in PTGS2, IL8, IL8RB, RNASEL, NOS2 and VEGF were associated with biliary tract cancer and/or stones." (PMID 23057767, 2012).
brain glioma (1 paper, 2018). A malignant glioma that involves the brain. "Furthermore, the silencing of NOS2 expression by RNA interference decreased in vitro brain glioma-initiating cells (GICs), highlighting the main role of NOS2 in GSC biology and maintenance." (PMID 30227679, 2018).
cardia cancer (1 paper, 2020). A malignant neoplasm involving the cardia of stomach. "Locally, cardia cancers were distinguished by comparatively high expression of NOS2, and tended to have seven-fold higher expression of IL10, which correlated positively with histological grade and, thus, with tumor aggressiveness." (PMID 32630408, 2020).
cholera (1 paper, 2022). "Cholera patients’ duodenum samples at the acute phase showed more abundant NOS2 and DUOX2 transcript levels compared to the convalescent phase." (PMID 35573801, 2022).
Coccidioides infection (1 paper, 2025). "In response to Coccidioides infection, Spp1+ macrophages express high levels of pro-inflammatory (Nos2, Tgfb1, Il1β, and Il6) and fibrotic/wound healing associated genes (Inhba, Spp1, Arg1, Pdgfb, and Fn1)." (PMID 40704794, 2025).
colon adenoma (1 paper, 2012). An adenoma that arises from the colon. "To investigate the potential for miRs to be involved in macrophage or NOS2- induced senescence, we also evaluated the association of microRNAs with macrophage infiltration and NOS2 in IBD, and colonic adenomas." (PMID 22970173, 2012). "We found that miR-21 expression is associated with high NOS2 and CD68 expression in UC and CD, as well as colon adenomas." (PMID 22970173, 2012).
dermatomyositis (1 paper, 2021). Dermatomyositis (DM) is a type of idiopathic inflammatory myopathy characterized by evocative skin lesions and symmetrical proximal muscle weakness. "At the same time, it was observed that MDA5 positive dermatomyositis patients specifically expressed NOS2 in sarcoplasmic muscle fibers and co-localized with the protective HP70 chaperone protein." (PMID 34966600, 2021). "Compared with typical dermatomyositis patients, the degree of IFN-related pathways activation in MDA5 positive patients was lighter, accompanied by a lower-activating state of STAT1, leading to a down-regulation of NOS2 expression in Th1 macrophages." (PMID 34966600, 2021).
dry eye (1 paper, 2025). "Specifically, we discovered that the decreased miR‐31‐5p level significantly correlated with higher NOS2 expression (r = −0.7056, p = 0.0337) in SS dry eye patients." (PMID 40068094, 2025).
dysplasia (1 paper, 2014). A usually neoplastic transformation of the cell, associated with altered architectural tissue patterns. "Over-expression of NOS2 has been found in dysplasia specimens and has also been involved in early cellular changes leading to malignity such as transformation of normal cells or growth of altered cells." (PMID 24316703, 2014).
endometrial cancer (1 paper, 2024). Primary or metastatic malignant neoplasm involving the endometrium (mucous membrane that lines the endometrial cavity). "Experimental studies suggest that changes in NOS2 expression may help predict endometrial cancer progression and treatment outcomes." (PMID 38706893, 2024).
Epstein-Barr virus infection (1 paper, 2024). An infection that is caused by Epstein-Barr virus. "Functional annotation clustering analysis revealed that, like in the endocrine cell populations, categories of “innate immunity,” “Epstein-Barr virus infection,” “viral entry,” and “interferon signaling” were increased in the NOS2+ non-endocrine cells." (PMID 38985000, 2024).